ICAM1 (intercellular adhesion molecule 1)
Diseases named in the same sentence as ICAM1 in open-access papers (continued):
Sharing a sentence is not in itself a finding about the gene and the disease.
tumor (continued). "In melanoma models, DAC cooperates with IL- 12, type I IFNs or ICAM-1 antibody drug conjugates to promote anti-tumor efficacy by sensitizing to direct tumor killing and by remodeling the TME." (PMID 40317004, 2025). "As for other endothelial adhesion molecules, interactions with ICAM-1 on the surface of endothelium and its ligands expressed by the tumor cells favor tumor dissemination to secondary sites." (PMID 40071851, 2025). "In CRC cells, TTP overexpression assisted haem oxygenase-1 (HO-1) in destabilizing intercellular adhesion molecule-1 (ICAM-1) mRNA at the post-transcriptional level, which was crucial for tumour-PBML interactions." (PMID 39718205, 2025). "Conversely, the targeted accumulation of ICAM‐1–Cy5.5 in the tumor region was clearly demonstrated through fluorescence microscopy examination of tumor tissue sections." (PMID 39996528, 2025). "Like TIMP1 and ICAM1, CTSD is typically overexpressed in PDAC and has been implicated in cancer cell proliferation, migration, and tumor invasion." (PMID 40507347, 2025). "While ICAM-1’s role in T cell crawling on initial lymphatics has been addressed, its specific role in tumor-infiltrating lymphocytes’ exit from tumors remains relatively unexplored." (PMID 40475782, 2025). "In the context of cancer, ICAM-1 has been studied for its potential role in tumor progression and the immune response against cancer cells." (PMID 40226632, 2025). "LFA-1-mediated binding to tumor vascular ICAM-1 facilitated nanoparticle accumulation at the tumor site." (PMID 40573997, 2025). "Ex vivo, neutrophils derived from tumor-bearing mice also killed cultured E0771 cells via ICAM-1-dependent interactions." (PMID 40475782, 2025). "The observed increase in T-cell and dendritic cell activation, along with promoted vascular normalisation in PAK1KO and PAK4KO tumours, was accompanied by elevated expression of ICAM-1 and VCAM-1." (PMID 40943273, 2025). "The anti-tumor N1 marker ICAM1 was detected at the mRNA level, but only a minimal ICAM1+ neutrophil population (1%) was observed." (PMID 40867260, 2025). "In contrast, the expression levels of MPO, ELA2, ARG1, and ICAM1 remained unchanged in all treatment groups, indicating that rhGDF15 and rhTNF-α have selective effects on tumor-promoting cytokine expression." (PMID 41035818, 2025). "VEGF and FGF2 induce endothelial anergy by suppressing vascular cell adhesion molecule 1 (VCAM‐1) and intercellular adhesion molecule 1 (ICAM‐1) expression, impairing leukocyte extravasation as well as tumour immune surveillance." (PMID 40268524, 2025). "In order to increase tumor‐targeting, TPNPs were combined with local low‐dose irradiation, which was shown to augment the expression of adhesion molecules (e.g., ICAM‐1) on tumor vasculature." (PMID 40708975, 2025). "This contrasts with the areas where tumor cells with high ICAM1 expression are clustered, exhibiting stronger staining." (PMID 39971940, 2025). "MS-based approaches detect critical cytokine- and growth factor-related proteins, such as VEGF, MMPs, and ICAM-1, which are involved in angiogenesis, tumor invasion, and immune modulation." (PMID 40881677, 2025). "We will first describe how LFA-1 generally promotes immune surveillance through its interactions with ligands, primarily its major ligand, ICAM-1, leading to leukocyte activation and tumor cell killing." (PMID 39911389, 2025). "Ruxolitinib, a selective JAK1/2 kinase inhibitor known to suppress JAK-STAT signaling, was used to assess the role of tumor-intrinsic IFN signaling in the elevated release of ICAM-1 and CXCL10." (PMID 40861475, 2025). "ICAM-1 on triple-negative breast cancer cells promotes tumor cell secretion of suPAR, a chemoattractant for neutrophils, and attaches to CD11b molecules on neutrophils to form CTC-neutrophil bonds." (PMID 40076927, 2025). "Tumor cells generate a perivascular system on organ surfaces via intercellular adhesion molecule-1 (ICAM-1), forming a vascular niche similar to ECs." (PMID 40821116, 2025).
tumor (continued). "Lidocaine and ropivacaine have been shown to inhibit Src activation and ICAM-1 phosphorylation in tumour cells." (PMID 40507646, 2025). "Recent studies have also shown that IFN-γ can increase contact-dependent killing by CAR-T cells through the upregulation of adhesion molecules, such as ICAM-1, on tumor cells." (PMID 39981247, 2025). "In vitro coculture experiments have demonstrated that LSECs and metastatic tumor cells interact via ICAM‐1/LFA‐1, promoting the release of tumor‐derived PGE‐2, IL‐6, VEGF, and MMPs, as well as LSEC‐derived IL‐1β, IL‐6, and TNF‐α into the TME." (PMID 40027151, 2025). "To test this, we introduced T cells to the SLB system, which we adapted to function as a minimal system for IS formation, by adding ICAM1 at 200 molecules/μm2 and mimicking the Her2High and Her2Low expression levels on tumor cells." (PMID 40445758, 2025). "Tumor resistance to NK cell-mediated cytotoxicity due to down-regulation of ICAM-1 and other strategies is hindering the development of NK cell-based immunotherapy." (PMID 41225536, 2025). "Tumor blood vessels often lack proper endothelial junctions and adhesion molecules, such as intercellular adhesion molecule-1 (ICAM-1) and vascular cell adhesion molecule-1 (VCAM-1), which are essential for T cell extravasation." (PMID 41048631, 2025). "Key transcription factors (TFs), such as CREB1, CIITA, and ICAM1, regulate the expression of immune-related genes, including those involved in antigen processing and HLA class I/II expression, thereby influencing tumor antigen presentation." (PMID 41312385, 2025). "CXCL10 and ICAM1 are essential for T cell trafficking and adhesion, which are critical for effective tumor localization and infiltration." (PMID 41293181, 2025). "For example, EGFR-CAR-T cells significantly inhibit TNBC growth in vitro and in vivo, and ICAM-1-specific CAR-T cells effectively reduce tumor growth by targeting ICAM-1-expressing TNBC cells." (PMID 40165974, 2025). "Transient local blockade of LFA-1/ICAM-1 functions offers an opportunity to attain systemic biodistribution of tumor-reactive T-lymphocytes." (PMID 40475782, 2025). "Metastatic cells can use leukocytes as bridging cells to promote adhesion through ICAM-1, an adhesion molecule present on the surface of endothelial and tumor cells." (PMID 39780275, 2025). "Meanwhile, FN1 secreted by CAFs enhances the expression of intercellular adhesion molecule 1, increases endothelial cell permeability, and facilitates the transendothelial migration of tumor cells, further promoting tumor cell extravasation." (PMID 40656546, 2025). "We showed that WT EVs promote tumor growth, directly increase endothelial cell abundance, and lower ICAM-1 surface expression in HuR-KO tumors." (PMID 40814996, 2025). "During early phases of tumor development, N1 TANs expressed high levels of TNF-α, ICAM-1, and Fas, promoting tumor cell apoptosis and enhancing CD8+ T-cell recruitment." (PMID 41584838, 2025). "The maturation rate of DCs in tumor‐infiltrating lymph nodes was also obviously increased by combination therapy with ICAM‐1–Dxd and B7‐H3‐CD3." (PMID 39996528, 2025). "Promisingly, ICAM1 has also emerged as a therapeutic target, with antibody-drug conjugates demonstrating strong anti-tumor efficacy in preclinical models." (PMID 41300430, 2025). "VP301, a bispecific CD38 and ICAM-1 antibody, was designed to leverage the overexpression of these antigens on MM cells to enhance immune-mediated tumor destruction." (PMID 40597436, 2025). "Tumor cells exploit LSECs through adhesion molecules such as intercellular adhesion molecule-1 (ICAM-1) and vascular cell adhesion protein-1 (VCAM-1), aiding liver colonization." (PMID 40563628, 2025). "ICAM-1 serves as a critical mediator in tumor progression and metastasis across various cancer types." (PMID 40597436, 2025). "We first determined the in vivo efficacy of ICAM1‐ICG‐mediated NIR‐pyroptosis in a subcutaneous ATC tumor model (8505C)." (PMID 40539828, 2025).
tumor (continued). "VCAM-1 and ICAM-1 mediate tumor cell adhesion to endothelial cells and the extracellular matrix, playing key roles in tumor progression, metastasis, and inflammation." (PMID 40652770, 2025). "In the late-stage setting, ICAM1 ADC treatment was initiated when the tumor volume reached approximately 500 mm3." (PMID 39971940, 2025). "ICAM1, involved in inflammatory responses, contributes to immune evasion in PDAC by regulating leukocyte trafficking and tumor-associated inflammation." (PMID 40226632, 2025). "ICAM-1 is an integrin ligand that regulates leukocyte-endothelial interactions and plays a crucial role in the structure of the tumor vasculature and T-cell trafficking into tumors." (PMID 40180890, 2025). "Neutrophils anchor CTCs to the endothelium of target organs through a contact‐dependent mechanism mediated by integrins on neutrophils binding to ICAM‐1 on tumor cells." (PMID 40979214, 2025). "This interaction, mediated via platelet integrin αIIbβ3 and tumor cell CD54 (ICAM-1), enhanced experimental lung metastasis by 65%." (PMID 41465254, 2025). "Tumor cells adhere to endothelial surfaces through adhesion molecules such as E-selectin, ICAM-1, and vascular cell adhesion molecule 1 (VCAM-1), facilitating both intravasation and extravasation." (PMID 39940643, 2025). "Upon T cell activation, the leukocyte function-associated antigen–1 (LFA-1) undergoes conformational changes that affect its affinity to the intercellular adhesion molecule–1 (ICAM-1) on tumor cells; this is central for the stability of the TCR IS." (PMID 39792660, 2025). "They found that neutralizing IL-6 prevented the selectin and Intercellular adhesion molecule-1 (ICAM-1) – dependent migration of adoptively transferred CD8+ T cells through the tumor vasculature." (PMID 40092992, 2025). "In comparison, ICAM1‐ICG or NIR laser irradiation alone showed only minimal impact on 8505C tumor progression." (PMID 40539828, 2025). "TNF-α and IFN-γ play roles in tumor cell killing and contribute to T cell-induced bystander tumor cell lysis by upregulating ICAM-1 and Fas." (PMID 39806405, 2025). "Rapid viral replication, effective internalization, and highly specific viral attachment are all made possible by the coordinated action of DAF and ICAM-1, which leads to tumor cell lysis." (PMID 41313526, 2025). "In relation with the CAR T-cells field, ICAM-1 at the surface of tumor cells was reported as a good target for CAR T-cells in reason of its wide expression across tumors." (PMID 40071851, 2025). "The upregulation of intercellular adhesion molecule-1 (ICAM-1) in tumor cells can mediate neutrophil targeting, so the neutrophil membrane PAM also has better targeting to tumor tissues." (PMID 40284476, 2025). "The data from the analysis of the proteomic profiles of PAK1KO and PAK4KO tumours have revealed that knockout of PAK1 or PAK4 upregulated ICAM-1, MHC class I molecules and enriched the expression of proteins involved in leukocyte trans-endothelial migration." (PMID 40943273, 2025). "To understand further how these CD3+ T cells are trafficked into the stroma, we also studied tumour associated BVs with the expression of the key molecules VCAM-1 and ICAM-1 that are involved in immune cell trafficking." (PMID 39792888, 2025). "In a 14‐day course, the 8505C tumor growth of the ICAM1‐targeted NIR‐pyroptosis groups was potently attenuated in comparison with the control groups." (PMID 40539828, 2025). "To answer this question, we investigated the in vivo efficacy of ICAM1‐ICG in combination with systemic PD‐1 antibody treatment in an immunocompetent murine tumor model." (PMID 40539828, 2025). "IFN-γ can facilitate tumor metastasis by inducing the expression of ICAM1 and CD13, promoting epithelial-mesenchymal transition (EMT), and stimulating the production of CXCR4 and MUC4." (PMID 40143164, 2025).
tumor (continued). "By activating LFA-1, 7HP349 enhances T cell adhesion to ICAM-1, leading to improved cell spreading and migration from the vasculature into the tumor microenvironment." (PMID 39911389, 2025). "It promotes the recruitment of T‐cells to inflammatory and tumor sites by enhancing their adhesion via ICAM‐1 and VCAM‐1 and modulating T‐cell activity through VEGFR‐1." (PMID 40944395, 2025). "Within the TME, migrated CTLs recruit LFA-1 to engage with ICAM-1 on tumor cells, forming a cytolytic synapse ultrastructure that facilitates their effector functions." (PMID 39911389, 2025). "For example, the binding to ICAM-1 on tumor cells can lead to the conjugation between NK cells and tumor cells, which results in the reorganization of cytoskeletal structures and lytic granule polarization within NK cells." (PMID 40103815, 2025). "PAK1KD inhibited tumour growth and was associated with reducing VEGFA-driven angiogenesis, promoting vascular normalisation and stromal or vascular changes associated with ICAM-1 expression, and reducing hypoxia." (PMID 41294859, 2025). "Adhesion molecules (e.g., LFA-1, CD103) can strengthen cell–cell contact by binding ligands, such as ICAM-1 and E-cadherin, on tumor cells." (PMID 40565031, 2025). "We observed that ICAM-1 surface expression in endothelial cells increased in HuR-KO tumors, suggesting an increase in inflammatory activation in HuR-KO tumor endothelial cells." (PMID 40814996, 2025). "For instance, Dicer deficiency in tumor cells leads to ICAM-1 upregulation, enhancing CTL–tumor cell conjugation and antigen-specific cytotoxicity." (PMID 40647470, 2025). "Specifically, within the liver microenvironment, liver sinusoidal endothelial cells (LSECs) exhibit elevated expression of VEGF and intercellular cell adhesion molecule-1 (ICAM-1), facilitating tumor cell adhesion and angiogenesis." (PMID 40823092, 2025). "In solid tumors, ICAM-1 facilitates tumor cell adhesion to the endothelium, promoting invasion and metastasis." (PMID 40597436, 2025). "Their work revealed that ionizing radiation induces GBM cells to shed soluble ICAM1 (sICAM-1) into the tumor milieu, which stimulates the infiltration of macrophages, thereby enriching the TME with inflammatory macrophages." (PMID 40838069, 2025). "Our comparative studies highlight the superior tumor-cell targeting and elimination capabilities of ICAM1-ADCs over conventional chemotherapy agents like Cis/Pac, in both in vitro and in vivo settings." (PMID 39971940, 2025). "To analyze the neutrophil properties, we used the following frequently mentioned profiles: pro-tumor anti-inflammatory profile (Mmp9, Vegfa, Arg1, Nos2, Ccl17, Il10) and anti-tumor pro-inflammatory profile (Icam1, Tnfa)." (PMID 40001601, 2025). "ICAM-1 was also intensely expressed within centralized tumor cells, as well as in the surrounding pseudo-palisade circular boundary." (PMID 38258133, 2024). "ICAM-1 correlates to larger tumor size, metastasis, and recurrence in HCC, leading to a poorer prognosis." (PMID 39132161, 2024). "Mechanism investigations further revealed that GM-CSF facilitated the upregulation of CD11b expression in neutrophils, enabling their interaction with ICAM1 on tumor cells." (PMID 38907234, 2024). "The intercellular adhesion molecule-1 (ICAM-1) also plays an essential function in immune reactions and cell–cell contact in the tumor environment." (PMID 38275400, 2024). "Disrupting ICAM-1‒FGG interaction prominently induces NSCLC cell apoptosis thus restraining tumor progression." (PMID 39168965, 2024). "ICAM-1 is also present on leukocyte- and tumour-cell-derived exosomes, small double-membrane extracellular vesicles formed within late endosomal compartments." (PMID 38391953, 2024). "In fact, T-cell-mediated tumor rejection is inhibited by blocking T-cell binding to either VCAM-1 or ICAM-1 on endothelial cells." (PMID 39596815, 2024).
tumor (continued). "The authors proved that silencing ICAM-1 expression significantly inhibited bone metastasis in tumor-bearing mice." (PMID 39199694, 2024). "Coculturing tumor cells with varying levels of ICAM1 expression alongside neutrophils enabled us to examine the MAPK signaling pathway in tumor cells." (PMID 38907234, 2024). "The study further reported the cancer-specific CBD-mediated LAK cell adhesion and lysis of cancer cells, without any indication of the LAK cell-mediated lysis and upregulation of ICAM-1 of the non-tumour bronchial epithelial cells." (PMID 38891847, 2024). "Through correlation analysis, we discovered a strong association between ICAM1 and neutrophils in the tumor microenvironment, particularly in TNBC, suggesting a potential interaction between ICAM1 and neutrophils in TNBC." (PMID 38907234, 2024). "ICAM-1 has been shown in studies to give primary tumor cells an invasive phenotype, stimulate the initiation and growth of tumors, and serve as a prognostic indicator." (PMID 38799250, 2024). "Coxsackievirus A21 (CVA21) has been shown to preferentially infect tumor cells via intercellular adhesion molecule 1 (ICAM-1) and decay-accelerating factor (DAF)." (PMID 39602056, 2024). "Similar to the observation in Hs 746T tumor model and ICAM-1 CAR T cells, PET-CT imaging showed continuous expansion of CAR T cells as the tumors progressed in mice receiving CAR T cells only." (PMID 38550578, 2024). "The results revealed significant direct contact between neutrophils and ICAM1 in untreated tumor tissues." (PMID 38907234, 2024). "Tumor endothelial cells altered glycosylation of ICAM-1, VCAM-1, and PECAM, and lectins, promoting tumor progression and metastasis, and modifying the adhesive properties of endothelial cells." (PMID 39035739, 2024). "ICAM-1, a cell surface glycoprotein, regulates the behavior of tumor cells by facilitating interactions with the cellular microenvironment and the extracellular matrix." (PMID 38502348, 2024). "Tumor ECs undergo genetic alteration, often with downregulated adhesion proteins, such as intercellular adhesion molecule 1 (ICAM-1) and vascular cell adhesion molecule 1 (VCAM-1) that are necessary for immune cell attachment and extravasation." (PMID 38580870, 2024). "ICAM‐1 was found to be an important regulator of angiogenesis and to accelerate the malignant process of tumour." (PMID 39021279, 2024). "Human and mouse cancer patients had CTC–neutrophil microaggregates in circulation; the CTCs included in the clusters were highly metastatic and proliferative, which is consistent with ICAM-1+ CTCs having higher levels of tumor stemness." (PMID 38786066, 2024). "CXCR3 activation mediates the interaction between CD8+ T LFA-1 and tumor ICAM-1, further promoting T cell adhesion and activation within the tumor microenvironment." (PMID 38953994, 2024). "Orthotopic models were used to isolate TAMs from WT and PGRN−/− mice, by flow cytometry; we did find that ICAM-1 was highly expressed in the TAMs of WT murine tumor tissue." (PMID 38554213, 2024). "Functional assessments of cell migration and invasion demonstrated that neutrophils substantially increased tumor cell invasion and migration, while ICAM1 knockdown mitigated the promoting effect of neutrophils on tumor cells." (PMID 38907234, 2024). "We found that tumor-infiltrating CD8+ T cells upregulated ICAM-1 expression to adapt to their unique function in the TME." (PMID 38169608, 2024). "Adoptive administration of ICAM-1 OE CD8+ T cells showed comparable effects on tumor control in primary tumors to those of WT CD8+ T cells." (PMID 38169608, 2024). "Bound neutrophils can both traffic the tumor cells across the endothelium through ICAM-1-β2 integrin interactions and act as a shield for cancer cells." (PMID 38671750, 2024). "The result of ICAM-1-targeted PET imaging revealed a significant reduction in ICAM-1 levels in the tumor following inhibition of T-cell migration with FTY720." (PMID 38169608, 2024).